FAT4 (FAT atypical cadherin 4)
Diseases named in the same sentence as FAT4 in open-access papers (continued):
Sharing a sentence is not in itself a finding about the gene and the disease.
van Maldergem syndrome (17 papers, 2016 to 2026). "Van Maldergem Syndrome (VMS) is a rare autosomal recessive disorder caused by pathogenic variants in the atypical cadherin genes DCHS1 or FAT4 and is marked by craniofacial, skeletal, and neurodevelopmental abnormalities." (PMID 41972678, 2026). "Mutations in the receptor-ligand cadherin pair DCHS1 (Dachsous cadherin-related 1) and FAT4 (FAT Atypical Cadherin 4) have been associated with the Van Maldergem syndrome, which is characterized by a periventricular neuronal heterotopia." (PMID 35069108, 2021). "Recent studies have demonstrated that mutations in the protocadherin genes DCHS1 and FAT4 are associated with Van Maldergem Syndrome." (PMID 33330619, 2020). "Fat4 and Dchs1 loss of function in mouse NSCs induced phenotypes resembling Van Maldergem syndrome with the formation of periventricular heterotopias." (PMID 32170161, 2020). "Biallelic mutations of FAT4 gene (FAT atypical cadherin) are associated with a rare autosomal recessive multiple malformation syndrome: the Van Maldergem syndrome (VMS), characterized by multiple bodily malformations (craniofacial, auditory, renal) and partially penetrant PH." (PMID 29946244, 2018). "Mutations in FAT4 may cause neuronal defects in addition to the well-known van Maldergem syndrome, characterized by intellectual disability, periventricular heterotopia, characteristic facial features, camptodactyly and syndactyly, small kidneys, osteoporosis, and tracheal anomalies." (PMID 37273692, 2023). "Fat4 and Dchs1 are receptor and ligand of the Hippo pathway, and mutations in FAT4 and DCHS1 cause Van Maldergem syndrome in humans." (PMID 32170161, 2020). "Mutations in FAT4 and DCHS cause Van Maldergem syndrome in humans, an autosomal-recessive disorder characterized by intellectual disability, auditory, craniofacial, skeletal, limb and renal malformations." (PMID 32170161, 2020). "FAT4 and DCHS1 are directly implicated in the cause of Van Maldergem syndrome, a developmental disorder characterized by PH and function upstream of MOB2 in the Hippo signaling pathway." (PMID 29593499, 2018). "Mutations in Fat’s closest mammalian homolog Fat4 (FatJ) and its Ds-like ligands strongly disrupt PCP-like processes, and have in humans been associated with the multisystem defects of Hennekam and Van Maldergem syndromes." (PMID 27692068, 2016). "Interestingly, the inheritable brain dysplasia Van Maldergem syndrome (VMS; MIM601390) results from mutations of the Hippo upstream regulators Dchs1 and Fat4, and the phenotype in relevant mouse models can be rescued by YAP inhibition." (PMID 27935819, 2017).
breast carcinoma (15 papers, 2007 to 2025). "Of relevance to breast cancer, it is notable that Fat4 deletion was reported to transform murine mammary cells." (PMID 40083689, 2025). "Regarding genes regulated by MMRs, we discovered a redundant regulation of the tumor suppressors FAT4 and KLF6, among others, whose loss of expression has been associated with a more aggressive phenotype in breast cancer." (PMID 32635183, 2020). "This indicated that the decrease in FAT4 expression was partly due to promoter methylation as previously reported in breast cancer and few stage I lung adenocarcinoma patients." (PMID 29435168, 2018). "The mechanism by which the MEK/Erk pathway represses FAT4 gene expression is conserved in even the malignant breast cancer cell line MDA-MB-231 cells as well as the normal breast cell line MCF-10A cells." (PMID 25679223, 2015). "We also found that MCF-7 breast cancer cells express far too low a level of FAT4 mRNA compared with the MCF-10A normal mammary cell line (data not shown)." (PMID 25679223, 2015). "To analyze the mechanisms that repress FAT4 gene expression in human breast cancer, we generated a model of carcinogenesis using MCF-10A cells, an immortalized normal human mammary epithelial cell line." (PMID 25679223, 2015). "The human FAT4 mRNA expression is repressed in 3 out of 6 breast cancer cell lines and in 3 out of 5 cases of primary breast cancers, partially due to promoter CpG hypermethylation." (PMID 23076869, 2012). "Moreover, breast cancer was one of the more obvious cancer types showing reduced FAT4 expression among TCGA datasets 55 with reduced FAT4 expression in TNBC tissues along with in vitro findings consistent with tumor suppressor function." (PMID 40083689, 2025). "In particular, FAT4 has been considered as a new biomarker for breast cancer prognosis." (PMID 36051999, 2022). "Similarly, in breast cancer, FAT4 silencing resulted in the upregulation of N-cadherin, MMP-7, and Cyr61 expression and the downregulation of E cadherin, indicating the role of FAT4 in the EMT process." (PMID 32366234, 2020). "Methylation of FAT4 has been reported previously in breast cancer." (PMID 29435168, 2018). "FAT4 knockdown increased the migratory and invasive ability of breast cancer cells." (PMID 29435168, 2018). "FAT4 is identified as a tumor suppressor gene in breast cancer, and lung cancer only in males." (PMID 27626693, 2016). "Reduced FAT4 gene expression in human breast cancers has been reported in several studies." (PMID 25679223, 2015). "The FAT4 gene is silenced by promoter hypermethylation in breast cancer cells." (PMID 25679223, 2015). "FAT4 is a member of the Hippo signaling pathway and has been classified as a putative tumor suppressor in breast cancer, although, this is a context-dependent designation as it has also been shown to play roles in tumorigenesis and planar cell polarity, a process linked to metastasis." (PMID 24944582, 2014). "FAT4 mRNA is repressed in breast cancer and lung cancer due to promoter hypermethylation." (PMID 23076869, 2012). "Therefore, we explored the effect of FAT4 on Wnt/β-catenin activation in breast cancer." (PMID 31695775, 2019). "FAT4 expression was different in different stages of bladder cancer (BLCA), kidney clear cell carcinoma (KIRC), and breast cancer (BRCA)." (PMID 36051999, 2022). "Altogether, our current study presents a novel model in which FAT4 represses YAP/TAZ activity by regulating actin structures, at least in breast cancer cells." (PMID 25679223, 2015). "In addition, to emphasize the importance of the MEK/Erk pathway in FAT4 mRNA repression we evaluated the effect of U0126 on FAT4 mRNA expression in MDA-MB-231 cells, a malignant breast cancer cell line." (PMID 25679223, 2015).
lung carcinoma (11 papers, 2012 to 2025). "In lung cancer patients, low expression of FAT4 associates with short survival, while its overexpression inhibits growth and migration of lung cancer cells and suppresses metastasis." (PMID 39478125, 2024). "Owing to hypermethylation in the promoter of gene, FAT4 expression is suppressed in lung cancer, enhancing its malignancy." (PMID 39323626, 2024). "FAT4 activation promotes autophagy in lung cancer cells, whereas its downregulation alters autophagic flux and leads to the accumulation of autophagosomes in photoreceptor neurons in Drosophila, thereby affecting cellular homeostasis." (PMID 37609821, 2023). "Our study aims to clarify the FAT4 expression patterns, as well as the significance of FAT4 in predicting the prognosis and cancer immunity to non‐small cell lung cancer (NSCLC)." (PMID 35770846, 2023). "Taken together, results of this study suggested that the inhibitory effect of YFJDT on EMT in lung cancer tumors is through upregulating FAT4, promoting autophagy, and thus inhibiting EMT in cancer cells." (PMID 35132327, 2022). "Epigenetic mechanism, i.e. promoter hypermethylation, was involved in FAT4 dysregulation in human breast and lung cancers." (PMID 26672766, 2016). "Emerging evidence suggests that the protocadherin FAT4 acts as a tumor suppressor in humans, and reduced FAT4 gene expression has been reported in breast and lung cancers and melanoma." (PMID 25679223, 2015). "In support of this finding, PrognoScan, a new microarray database, and other recent studies have demonstrated that human FAT4 gene expression is repressed in breast and lung cancers and in melanoma, which suggests that reduced FAT4 gene expression can trigger carcinogenesis." (PMID 25679223, 2015). "Despite identifying the role and interaction proteins of FAT4 in vertebrates, the role of FAT4 in tumors has not been well studied, especially in lung cancer." (PMID 35770846, 2023).
colon cancer (8 papers, 2015 to 2024). "Additionally, we examined the co-occurrence of mutations in TSPs and colon cancer mutation-prone genes, and found that TSPs coexisted mutationally with MUC16, FAT4, OBSCN, and ZFHX4." (PMID 38827236, 2024).
lymphedema (8 papers, 2021 to 2025). Excess fluid collection in tissues, causing swelling. "Abnormal valve development in mice with defective Dchs1 and Fat4 genes causes blocked lymphatic fluid flow and triggers primary lymphedema." (PMID 40766782, 2025).
melanoma (8 papers, 2012 to 2025). A malignant, usually aggressive tumor composed of atypical, neoplastic melanocytes. "Non-synonymous FAT4 mutations are also detected in 4 out of 6 cases of melanomas using the whole-exome sequencing approach and in 2 out of additional 9 cases of melanomas using the candidate-exons sequencing approach." (PMID 23076869, 2012). "Finally, FAT4 is known to inhibit cell growth by activation of the Hippo pathway and the FAT4 gene is recurrently mutated in several types of human cancer including melanoma." (PMID 23720711, 2013). "FAT4 has been demonstrated in human cancer, including melanoma." (PMID 35524260, 2022).
hepatocellular carcinoma (6 papers, 2012 to 2023). A malignant tumor that arises from hepatocytes. "Studies suggested FAT4 expression was reduced in gastric adenocarcinoma and hepatocellular carcinoma tumor tissues, and FAT4 downregulation was associated with tumor grade." (PMID 36051999, 2022). "Non-synonymous FAT4 mutation is detected in 1 out of 10 cases of hepatocellular carcinoma using the whole-exome sequencing approach." (PMID 23076869, 2012). "The findings were consistent with the results of a previous study that indicated that FAT4 deficiency may lead to uncontrolled tumor progression and unfavorable clinical outcome in hepatocellular carcinoma." (PMID 36051999, 2022). "A study of patients with hepatitis B virus (HBV)-associated hepatocellular carcinoma showed that the FAT4 (FAT atypical cadherin 4) gene might act as a tumor suppressor gene, which is inactivated in cases with hepatocellular carcinoma, but also in various other human cancers." (PMID 37108169, 2023).
cyst (5 papers, 2014 to 2023). A sac-like closed membranous structure that may be empty or contain fluid or amorphous material. "FAT4 plays a role in polarization of LECs since cyst-like lymphatics are detected in Fat4-deficient mouse embryos." (PMID 36895637, 2023). "The fact that inactivation of the central PCP molecule Fat4 in the kidney leads to cyst formation is perhaps the strongest evidence generated to date to suggest that disruption of PCP in the kidney leads to cyst formation." (PMID 26529018, 2015). "Disruption of the PCP-related protocadherin Fat4, which localizes in the primary cilia, leads to cyst formation, suggesting that cilia may be necessary for OCD to prevent tubular dilation." (PMID 36627370, 2023). "Compound loss of Fat4 with Vangl2 in mice, however, does enhance the cystic phenotype compared to Fat4 loss alone, and raises the question as to whether FAT4 interacts with core PCP proteins to modulate cyst expansion in PKD." (PMID 33716764, 2021). "Mutations in the PCP-associated genes Wnt9b and Fat4 have been shown to lead to cyst formation in postnatal kidneys while other murine PCP gene mutations that are homozygous lethal, like Vangl2, show early hallmarks of cyst formation such as dilated tubules." (PMID 24852369, 2014).
endometrial cancer (4 papers, 2020 to 2023). Primary or metastatic malignant neoplasm involving the endometrium (mucous membrane that lines the endometrial cavity). "Downregulation of FAT4 expression was significantly associated with lymph node invasion and poor survival in gastric and endometrial cancer." (PMID 32366234, 2020). "In endometrial cancer, the downregulation of FAT4 is due to the silencing of the deubiquitinating enzyme USP51, which exerts a tumor suppressor effect." (PMID 35770846, 2023). "Immunohistochemical analysis clarified lower FAT4 expression in gastric, colorectal, and endometrial cancer." (PMID 35770846, 2023). "In gastric and endometrial cancer cells higher level of nuclear YAP was observed following FAT4 repression." (PMID 32366234, 2020). "In endometrial cancer, FAT4 downregulation was attributed to the silencing of USP51, a de-ubiquitinating enzyme, suggested as a direct interacting partner of FAT4, contributing to its tumor suppressor role." (PMID 32366234, 2020). "Additionally, there has been a study indicating that FAT4 inactivation promoted migration and invasion of endometrial cancer cells via inhibiting the Hippo pathway." (PMID 36051999, 2022). "In a previous study, immunohistochemical analysis revealed lower FAT4 expression in gastric, colorectal, and endometrial cancer, when compared to adjacent non-cancerous tissues." (PMID 32366234, 2020).
diabetes (3 papers, 2023 to 2025). "In the context of diabetes mellitus (DM), the upregulation of m6A modification mediated by METTL3 suppresses the expression of key genes, including PKC-η, FAT4, and PDGFRA." (PMID 41315216, 2025).
glioma (3 papers, 2024 to 2025). A benign or malignant brain and spinal cord tumor that arises from glial cells (astrocytes, oligodendrocytes, ependymal cells). "Meanwhile, Notch1 pathway‐related genes, including Maml2, Ccn3, Fat4, Cdh6, and Ptp4a3, exhibited similar expression trends and may be intimately linked to glioma development." (PMID 39544152, 2024). "EGFR, FAT4, and BCOR were the three features associated with 64% ACC using the TCGA-UCI glioma grading set aimed at tumor grading." (PMID 40362575, 2025). "EGFR, FAT4, and BCOR were the three features associated with 64% ACC using the TCGA glioma grading set." (PMID 40362575, 2025). "When employing the TCGA-UCI glioma grading dataset, the most discriminative and significant three features (63.6% ACC) are EGFR, FAT4, and BCOR." (PMID 40362575, 2025).
lung adenocarcinoma (3 papers, 2012 to 2023). A carcinoma that arises from the lung and is characterized by the presence of malignant glandular epithelial cells. "FAT4 mRNA and protein expressions were both underregulated in NSCLC and associated with poor prognosis in both lung adenocarcinoma (LUAD) and lung squamous cell carcinoma (LUSC)." (PMID 35770846, 2023). "FAT4 promoter is hypermethylated in 7 out of 18 cases of lung adenocarcinoma (stage I) and FAT4 mRNA is downregulated in 18 out of 23 cases of non-small cell lung tumors (stage I or II)." (PMID 23076869, 2012).
lymph node metastasis (3 papers, 2018 to 2023). "Cox multivariate analysis showed that TNM stages, distant and lymph node metastasis, Lauren classification and FAT4 expression were independent prognostic factors in GC." (PMID 29435168, 2018). "FAT4 expression was lower in GC patients with lymph node metastasis (48.4%, or 137/283) than patients without lymph node metastasis (75.9%, or 126/166, P<0.05)." (PMID 29435168, 2018). "FAT4 expression was similar between cancer and adjacent noncancerous tissues in patients without lymph node metastasis." (PMID 29435168, 2018). "The GC patients with lymph node metastasis exhibited higher FAT4 methylation than patients without lymph node metastasis (38.2% vs. 14.0%, P<0.05)." (PMID 29435168, 2018). "Cox multivariate analysis indicated that TNM stage, distant metastasis, lymph node metastasis and vascular invasion were independent prognostic factors (P<0.05), but, FAT4 methylation status was not an independent prognostic factor (Hazard Ratio=0.160, P=0.689)." (PMID 29435168, 2018).
ovarian carcinoma (3 papers, 2020 to 2024). A malignant neoplasm originating from the surface ovarian epithelium. "The obtained data shed some light on the role of the FAT4 adhesion molecules in ovarian cancer tumorigenesis through different pathways, namely, Hippo, and Wnt-β-catenin." (PMID 32366234, 2020). "We evaluated the expression of FAT4 in ovarian cancer cell lines (MCAS, OVSAHO, A2780, A2780 cis), and normal (HOSE 6–3) cell line, using qRT-PCR and Western Blotting." (PMID 32366234, 2020). "Bioinformatics analysis of Human samples revealed similar results, showing downregulation of FAT4 expression in Human ovarian cancer samples as compared to normal tissues." (PMID 32366234, 2020). "We have performed cell viability, colony formation, and invasion assays in ovarian cancer cells treated with siRNA to knockdown FAT4 gene expression." (PMID 32366234, 2020). "Similar results were obtained by western blot analysis of FAT4 protein expression in ovarian cancer cells." (PMID 32366234, 2020). "To evaluate the role of FAT4 on ovarian cancer cell proliferation, we knocked-down FAT4 in MCAS and OVSAHO ovarian cancer cell lines, using siRNA." (PMID 32366234, 2020). "We hypothesized that FAT4 exerts its effect on the tumor characteristics of ovarian cancer cells through Hippo, apoptotic, retinoblastoma, and Wnt pathways." (PMID 32366234, 2020). "We performed cell invasion assay to investigate whether FAT4 regulates invasiveness in ovarian cancer cell lines." (PMID 32366234, 2020). "As for the signaling pathways involving FAT4 in cancer, a recent study has reported FAT4 silencing to enhance EMT and invasiveness of ovarian cancer by regulating YAP and β-catenin activity." (PMID 39323626, 2024). "Although OVSAHO represents high grade serous ovarian cancer, the expression of FAT4 was similar to that of MCAS, a low-grade ovarian cancer cell line." (PMID 32366234, 2020). "FAT4 expression was weaker in ovarian cancer cell lines, with MCAS and OVSAHO displaying higher expression as compared to A2780 and A2780 cis ovarian cancer cell lines." (PMID 32366234, 2020). "In previous studies, bioinformatics analysis indicated lower FAT4 expression in ovarian cancer tissues compared to that in normal tissues." (PMID 35770846, 2023). "Lower expression of FAT4 was observed in ovarian cancer cell lines and human samples as compared to non-malignant tissues." (PMID 32366234, 2020).
bladder cancer (2 papers, 2022).